RUNX2 (RUNX family transcription factor 2)
Diseases named in the same sentence as RUNX2 in open-access papers (continued):
Sharing a sentence is not in itself a finding about the gene and the disease.
osteoarthritis (continued). "During osteoarthritis progression, production of ECM components is substantially altered, including collagen I, collagen II, aggrecan, and Runx‐2, which changes the microenvironment of the cartilage and disrupts its integrity." (PMID 34078001, 2021). "This is especially the case for the switch of a RUNX2+ to SOX9+ cell fate, since epigenetic regulation has likely occurred in the process of osteoarthritis." (PMID 34869253, 2021). "HDACs can also affect certain pathways and transcription factors, such as runt-related transcription factor 2 (RUNX2), which mediates MMP-13 expression in osteoarthritis." (PMID 32722615, 2020). "However, there is some debate regarding the pathogenic effects of RUNX2 in osteoarthritis because no reported evidence suggests the altered occurrence of osteoarthritis in patients with cleidocranial dysplasia compared with other populations (personal communication)." (PMID 32079226, 2020). "Chondrocyte hypertrophy, regulated by Runt-related transcription factor 2 (RUNX2) and matrix metalloproteinase 13 (MMP13), is a crucial step in cartilage degeneration and osteoarthritis (OA) pathogenesis." (PMID 27563877, 2016). "Remarkably, inhibition of Hh in explant cultures of human osteoarthritic cartilage samples blocked expression of key genetic markers of osteoarthritis, including the metalloproteinases ADAMTS5 and MMP13, the transcription factor RUNX2, and COL10A131." (PMID 25992955, 2015). "HIF-2α is involved in a pathway that promotes osteoarthritis degradation and regulates the expression of genes related to chondrocyte hypertrophy and differentiation, such as COL10A1 and RUNX2, and the expression of genes related to ECM degradation, such as MMP9, MMP13, MMP3, ADAMTS." (PMID 36503684, 2022). "The results demonstrated that miR-92a was downregulated in equine synovial fluid from horses with severe osteoarthritis and there was a significant increase in COMP, COL1A2, RUNX2 and SOX9 following miR-92a mimic treatment of equine chondrocytes in monolayer culture." (PMID 36555166, 2022). "To clarify the relationship between P-15 regulation of chondrocyte proliferation and SFPQ-Akt-RUNX2 pathway, we chemically detected the expression of SFPQ and RUNX2 in the bone joint samples from clinical osteoarthritis and non-osteoarthritis patients." (PMID 36915153, 2023). "There is no doubt that SFPQ is a key regulator of the RUNX2 gene, and targeting the SFPQ site may be a potential strategy for the treatment of osteoarthritis, and even various human cancers that presence of high levels of RUNX2." (PMID 36915153, 2023).
leukemia (45 papers, 2010 to 2025). A malignant (clonal) hematologic disorder, involving hematopoietic stem cells and characterized by the presence of primitive or atypical myeloid or lymphoid cells in the bone marrow and the blood. "The RUNX gene family is intimately involved in carcinogenesis: the RUNX1 gene was found to be mutated in human leukemia; and RUNX2 is overexpressed in osteosarcoma and regulates bone remodeling and osteoclast differentiation." (PMID 35522574, 2022). "In contrast to RUNX1 and RUNX3, whose mutations are closely linked to the promotion of leukemia and GC, respectively, the initial studies suggest that RUNX2 acts as a master regulator of osteoblast differentiation and bone development." (PMID 33313404, 2020). "Runx2 is a member of the runt family of transcription factors that has been linked to a variety of human cancers such as leukemia and gastric cancer." (PMID 21437219, 2011). "Together, these results show that high levels of expression of 2 key genes associated with a worse prognosis (ie, RUNX2 and MEIS1) are associated with nearby enhancer activity that is specific to an individual leukemia." (PMID 40729681, 2025). "When important oncogenes such as MEIS1 and RUNX2 are overexpressed because of novel enhancer usage, this has clear implications for therapeutic response and patient outcomes in leukemia." (PMID 40729681, 2025). "Ectopic RUNX2 expression in naïve-derived CAR T cells resulted in superior clearance of leukemia, higher proportions of cells in the marrow, and reduced proportions of cells displaying terminally exhausted phenotypes relative to control." (PMID 38196657, 2023). "RUNX2 overexpression in CAR8ND strongly enhanced leukemia clearance and increased CAR proportions and absolute numbers in the marrow at 11 days post-CAR infusion." (PMID 38196657, 2023). "RUNX2 overexpression boosts leukemia clearance, CAR T cell potency and CAR proportions in bone marrow." (PMID 38196657, 2023). "RUNX1 and RUNX2 expression was found to be quite high in head and neck cancer, kidney cancer, leukemia, and pancreatic cancer, according to our findings." (PMID 35522574, 2022). "PROM1, FLT3, CTGF, LGALS1, IGFBP7, ZNRF1, and RUNX2 were found highly expressed in the MLL-R pro-B ALL compared to the other subclassification of leukemia." (PMID 36276286, 2022). "pDC-specific super-enhancer of RUNX2 induces high expression of MYC in leukemia cells, and promotes the survival and proliferation of BPDCN cells." (PMID 33712565, 2021). "Studies in mice show that decreased RUNX2 activity slows CBFβ-SMMHC induced leukemia, while increased RUNX2 expression accelerates it." (PMID 27542261, 2016). "Similar to RUNX1, the strongest evidence for a pro-oncogenic function for RUNX2 comes from studies in lymphoma/leukemia models; however RUNX2 was also shown to play a role in invasive bone, breast, prostate, thyroid and pancreatic cancer." (PMID 24124450, 2013). "Ablation of Runx1 activity leads to leukemia and disruption of Runx2 results in deregulated cell proliferation and immortalization." (PMID 20863401, 2010). "In a mouse screen for c-Myc-collaborating oncogenes, MLV-induced leukemia occurred most frequently when the provirus integrated into the Runx2 locus resulting in its ectopic expression." (PMID 20863401, 2010). "In addition, overexpression of RUNX2 has also been identified in several human malignancies, including lymphoma/leukemia, bone, breast, prostate, thyroid and pancreatic cancers." (PMID 24124450, 2013). "Furthermore, the increase in Runx2 levels reduced leukemia median latency." (PMID 29755956, 2018). "Four of these genes were reported for leukemias (IRS1, RUNX2, CCDC50 and ROBO3) and four others were reported to be involved in other types of cancers (NSG1, CAMK1D, CD3E, KLF8)." (PMID 41146244, 2025).
leukemia (continued). "ChIP–seq profiling of Stat5a, Runx1 and Runx2 confirmed the motif analysis, demonstrating cobinding of these transcription factors and BAF or MLL1 and MLL4 complexes at key pro-leukemia genes including Hoxa7 and Hoxa9." (PMID 37580596, 2023). "RUNX2 upregulation favours the migration of T‐ALL cells and progression in leukaemia, while it regulates progression in renal cell carcinoma." (PMID 36264762, 2022). "Accordingly, reduction of Runx1 or Runx2 expression inhibited CBFβ–SMMHC-mediated differentiation block in embryos and leukemia onset in mice." (PMID 29755956, 2018). "High expression of ARID2, JMJD1C, MBNL1, MEF2C, or RUNX2 alone is associated with at least one indicator of poor prognosis in ALL patients, and CPEB2, MBNL1, RUNX2, and ZEB2 are all specifically overexpressed in MLL-FP leukemias." (PMID 28076791, 2017). "Among the TFs that we and others identified to be selectively essential and overexpressed in KMT2A-rearranged leukemia, MEF2C, RUNX2, and MEIS1 are well-established direct targets of KMT2A fusion oncoproteins, prompting us to consider that one of these TFs drives IRF8 overexpression." (PMID 35301220, 2022). "In leukemia cell lines HL60 and Jurkat, and CD34+ progenitor cells, induction of the Wnt/β-catenin signal increases the expression of the RUNX1 P1 isoform, which may be critical for leukemia onset and progression; in colon cancer cells, RUNX2 was found to be upregulated by the same pathway." (PMID 36429115, 2022). "Re-expression of WT but not KR mutant PKM2 inhibited the expression of RUNX1, but not the other core-binding factor family members RUNX2 or RUNX3 in NB4, U937 and 32DBCR-ABL leukemia cells, suggesting that SUMOylation of PKM2 is essential in modulating RUNX1." (PMID 33473116, 2021). "In non-MLL-rearranged leukemia, such as Npm1c/Flt3-ITD, we have also demonstrated a role for leukemia-specific interactions of COMPASS complexes with TFs resulting in altered accessibility at Stat5a and Runx2 loci and consequent transcriptional dysregulation." (PMID 40523422, 2025). "Interestingly, RUNX2, MBNL1, JMJD1C, SENP6, MEF2C, and ZEB2 are also hypomethylated in MLL-FP samples compared to either normal cells or other leukemias (not shown)." (PMID 28076791, 2017).
diabetes (40 papers, 2015 to 2026). "To detect possible changes in the bone cellular differentiation rate caused by diabetes, we evaluated the number of RUNX-2-positive cells via immunostaining." (PMID 26270535, 2015). "In addition, the phytoestrogen genistein has also been reported to prevent diabetes-related bone loss by stimulating the β-catenin/Runx-2 pathway, leading to the expression of bone protector osteoprotegerin protein." (PMID 40243576, 2025). "In addition, we observed that 1,25D remarkably ameliorated osteogenic phenotypic markers such as Ocn and Runx2 and rescued diabetes‐induced bone loss in vivo." (PMID 33609082, 2021). "Another study highlights RUNX2’s rolein promoting aortic fibrosis and stiffness, particularly in the context of type 2diabetes mellitus." (PMID 39484128, 2024). "Runx2 expression is improperly regulated by diabetes mellitus illness, which worsens aortic stiffness." (PMID 37728820, 2023). "On day 28 post-fracture, our 2-way ANOVA evidenced a significant main effect of diabetes on Col1a1 (p=0.0002), Runx2 (p=0.0008), and Osx (p=0.01) expression when comparing diabetic and non-diabetic rats." (PMID 36060973, 2022). "Our earlier studies demonstrated that p-AMPK drives MSCs to become osteocytes, whereas under diabetes conditions, the loss of AMPK activity correlates with ubiquitination of RUNX2 and favors adipogenesis." (PMID 35672290, 2022). "The Runx2 transcription factor is a key regulator of the VIC transition towards an osteoblastic phenotype as a response to various conditions such as diabetes, hyperlipidemia, or advanced age." (PMID 35409184, 2022). "The expression of protein Rankl was significantly increased and the expressions of proteins BMP2, OPG, OPN, and Runx2 were significantly decreased in diabetic mice (Diabetes-control, D-control) compared with normal mice (Wild-control, W-control) (p < 0.05)." (PMID 36632609, 2021). "Diabetes drives Runx2 expression and induces the osteogenic differentiation of both VSMCs and macrophages." (PMID 31924749, 2020). "Conversely, the targeted disruption of Runx2 appears to be beneficial for attenuating atherosclerotic calcification, especially in diabetes." (PMID 31924749, 2020). "An 80% reduction in SIRT1 levels was observed in patients with diabetes, both in serum and the arterial smooth muscle layer, whilst both RUNX2 and Osteocalcin levels were elevated." (PMID 30696833, 2019). "Exposure to high glucose and streptozotocin-induced diabetes models shows that stabilization of RUNX2 depends upon AMPK activation, and our in vitro kinase assays showed that AMPK phosphorylates RUNX2 at S118." (PMID 29988028, 2018). "The gene expression (mRNA) of osteocalcin and alkaline phosphatase levels in bone marrow cells explained the decreased osteogenic markers in diabetes except RUNX2." (PMID 29988028, 2018). "Our real-time PCR experiments highlight the maintenance of RUNX2 mRNA level in both in vitro adipogenic differentiation and diabetes-induced streptozotocin model of bone marrow cells." (PMID 29988028, 2018). "Expression of runt-related transcription factor-2 (Runx-2), a master gene of osteogenesis was shown to be significantly decreased in an intramembranous bone healing type 1 diabetes mellitus model." (PMID 28852138, 2017). "The diabetic rats displayed fewer RUNX-2-positive cells than the control rats at 30 days after diabetes induction." (PMID 26270535, 2015). "PAI-1 deficiency rescued diabetes-induced trabecular bone loss as well as the bone expressions of Runx2, Osterix, and ALP in female mice, but not male." (PMID 39388484, 2024). "In diabetes mellitus, RUNX2 contributes to ECM remodeling and aortic stiffening." (PMID 39484128, 2024). "Reduced RUNX2 in T2D postmenopausal women also confirms previous findings and further supports the notion of reduced osteoblast differentiation or function in diabetes." (PMID 38598270, 2024).
diabetes (continued). "MR409 treatment reduced ROS production and the expression of these osteogenic molecules, suggesting that MR409 may reduce VC via the inhibition of ROS/Runx2 in diabetes." (PMID 36742073, 2023). "Because a correlation between low RUNX2 expression and hypoxic conditions has been shown and because hypoxia has also been reported in diabetes mellitus, it can be concluded that the reduced RUNX2 expression is related to the hypoxic conditions in diabetic bone." (PMID 36499493, 2022). "AdipoRon suppressed the expression of protein Rankl and promoted the expressions of BMP2, OPG, OPN, and Runx2 in diabetic mice significantly (p < 0.05), which suggested that AdipoRon suppressed the diabetes-induced osteoclast formation and promoted the osteoblast differentiation in diabetic mice." (PMID 36632609, 2021). "In type 2 diabetes mellitus, increased glucose levels lead to increased expression of the runt-related transcription factor (Runx2), also known as the core binding factor alpha-1 (Cbfa-1), and growth factor bone morphogenic protein (BMP-2)." (PMID 34203711, 2021). "Notably, Stat1 acts as a positive transcription factor by directly binding to the promoter of Runx2 and promoting atherosclerotic calcification in diabetes." (PMID 31924749, 2020). "In addition, PARP-1 inhibition downregulates Stat1/Runx2 transcriptional activity and alleviates atherosclerotic calcification in diabetes." (PMID 31924749, 2020). "Clinical correlation of metformin restricts diabetes-induced bone adipogenesis, might be due to stabilization of RUNX2." (PMID 29988028, 2018). "In rat models of streptozotocin-induced diabetes, fluctuations inblood glucose levels exacerbate aortic fibrosis by affecting the reactive oxygen species (ROS)/p38MAPK/RUNX2 signaling pathway, highlighting the multifaceted role of RUNX2 inmetabolic stress conditions." (PMID 39484128, 2024). "Thus, we surmise that attenuation of VC by MR409 may be through upregulation of Klotho, which inhibits ROS and Runx2-mediated osteogenic transdifferentiation of VSMCs in diabetes." (PMID 36742073, 2023). "Thus, Runx2 is an important contributor to CAVD in diabetes/diabetic conditions." (PMID 34561944, 2021). "The efficient targeting of RUNX2, together with the advances in uncovering the significant molecules/pathways involved in VECs and VICs phenotypic alterations in diabetes, opens new avenues for developing innovative nanotherapeutics for the aortic valve disease in diabetes." (PMID 34561944, 2021). "In addition, the decreased expression of Runx2 in diabetes further inhibits osteoblastogenesis." (PMID 30459613, 2018). "Taken together, these results suggest that diabetes may lead to an imbalance in bone formation processes due to defects in cellular differentiation resulting from the decreased expression of transcription factors such as RUNX-2." (PMID 26270535, 2015). "BCAT2-mediated histone propionylation up-regulated RUNX2 expression, resulting in VSMC osteoblastic differentiation and the development of VC in diabetic plaques." (PMID 41503231, 2026). "In vitro studies have revealed that scopoletin (1–20 μM) improves osteoclast formation in diabetes through RANKL and enhances osteoclast formation in diabetes by inducing BMP-2 and Runx2." (PMID 38464713, 2024). "On the other hand, mRNA expressions of DKK1, BMP-2, OSN, RUNX2, and LRP5, which decrease with diabetes in bone tissue, increase significantly with MF administration." (PMID 39202505, 2024). "In comparison to the control group, the mean values of Runx2, β-catenin, and RANKL were significantly greater in the two diabetes groups, with significantly higher levels found in diabetic patients with VC." (PMID 37728820, 2023). "PARP1 knockout can inhibit the signal transducer and activator of transcription 1 (STAT1)/RUNX2 axis and reduce AIC in diabetes." (PMID 37679327, 2023).
diabetes (continued). "As expected, the thoracic aorta of DVC mice had significantly higher ALP activity, calcification and levels of RUNX2 and BMP2 compared to animals in the ND group, suggesting the successful establishment of a diabetic vascular calcification model." (PMID 35842695, 2022). "RT‐PCR revealed significantly up‐regulation of calcification markers in diabetic aortas, including Runx2 and OCN, suggesting that diabetes induced vascular calcification." (PMID 33724642, 2021). "Mechanistically, BCAT2-mediated BCKA-derived prop-CoA generation promotes propionylation at lysine 23 of histone H3 (H3K23pr), which contributes to the activation of RUNX2 expression, thereby accelerating VSMC osteoblastic differentiation and VC in diabetic plaques." (PMID 41503231, 2026). "Studies show that anthocyanins in black rice extract (0.5, 1.0 and 2.0 g/kg/day for 8 weeks) can improve bone loss in diabetes rats by inhibiting bone turnover and bone marrow fat production, and up regulating the ratio of RUNX2 and OPG/RANKL in bone tissue of diabetes rats." (PMID 40626227, 2025). "We also observed that diabetic mice exhibited significantly higher Col1 (late markers of bone formation) and RANKL mRNA expression, and lower OPG and RUNX2 (early markers of bone formation) mRNA expression than mice without diabetes." (PMID 39770498, 2024). "Diabetic mice exhibited significantly higher Col1 and RANKL mRNA expression and lower OPG and RUNX2 mRNA expression than those without diabetes (p < 0.05)." (PMID 39770498, 2024). "PARP1 knockout can inhibit the STAT1/RUNX2 axis and reduce AIC in diabetes." (PMID 37679327, 2023). "Diabetes-induced high glucose levels are known to downregulate RUNX2; however, the mechanisms involved are not clear." (PMID 35672290, 2022). "AMPK activity in various differentiation and transdifferentiation models and diabetes-induced bone adipogenesis studies exhibited that both AMPK and RUNX2 are synergistically regulated during adipogenesis and osteogenesis, further, this study shows that RUNX2-S118 phosphorylation is critical." (PMID 29988028, 2018).